TYR (tyrosinase)
Diseases named in the same sentence as TYR in open-access papers (continued):
Sharing a sentence is not in itself a finding about the gene and the disease.
melanoma (continued). "For this purpose, impacts of extracts and essential oil of R. × damascena were investigated on cell viability, cellular tyrosinase, melanin content, mushroom tyrosinase, reactive oxygen species (ROS) production, as well as the amount of tyrosinase protein in the B16F10 murine melanoma cell line." (PMID 37605721, 2023). "In addition, VIM, TTR, and TYR genes were used to evaluate the diagnosis of melanoma, which suggested VIM and TYR involved in pigment synthesis, and the mechanism of action needs further study." (PMID 37402463, 2023). "Results showed that 7H-4M treatment induced melanin synthesis and TYR in B16F10 melanoma cells." (PMID 37049801, 2023). "Also, this investigation aimed to provide an appropriate nano platform for enhancing anti-melanoma, anti-tyrosinase, and antibacterial GA." (PMID 38139807, 2023). "There are some applications in which several biosensors are for the detection of several diseases Lactate dehydrogenase (LDH) is the earliest prognostic biomarker of melanoma as well as serum s100B level, BRAF V600, Tyrosinase mRNA are the biomarkers used for the detection of melanoma." (PMID 37803407, 2023). "Thus, this work aimed to assess for the first time the in vitro anti-melanoma, anti-melanogenic, and anti-tyrosinase properties of three minor phytocannabinoids from hemp, namely cannabigerol (CBG), cannabinol (CBN), and cannabichromene (CBC)." (PMID 37242431, 2023). "Furthermore, compound 38a reduced melanin content in α-MSH and IBMX-stimulated B16F10 melanoma cells in a dose-dependent manner by decreasing the intracellular TYR activity level." (PMID 37240442, 2023). "Dendropanax morbifera leaves and stems-derived nanovesicles could reduce melanin content and inhibit tyrosinase (TYR) activity in melanoma cells in a concentration-dependent manner." (PMID 38001440, 2023). "Tyrosine analog, which is the substrate of the melanin-forming enzyme tyrosinase, may be the best candidate for the development of specific melanoma-targeting drugs and therapies." (PMID 36982309, 2023). "However, there was a dose-dependent decrease in intracellular tyrosinase activity in B16F10 melanoma cells after treatment with C. racemosa at concentrations of 2.5–25 μg mL−1." (PMID 37109464, 2023). "In particular, boron derivatives of naturally occurring L-tyrosine and L-dope amino acids, both precursors of melanin and substrates for tyrosinase, were synthesized and shown to have enhanced selectivity toward SK-23 melanoma cells with high tyrosinase expression." (PMID 37444386, 2023). "Other reports revealed that melatonin in human melanoma cells may both stimulate TYR activity in Sk-Mel-28 cells and decrease melanogenesis in highly pigmented MNT-1 cell lines." (PMID 37834395, 2023). "Thus, the cactus extract was shown to function as a potential inhibitor of IBX-stimulated tyrosinase production in B16-F10 melanoma cells." (PMID 36627306, 2023). "Tyrosinase is also used as an immunohistochemical marker in the diagnosis of melanoma." (PMID 37504268, 2023). "Alterations in melanin or dopamine synthesis enzymes, including tyrosinase (TYR) and tyrosine hydroxylase (TH), may also contribute to increased vulnerability to both melanoma and PD." (PMID 37629650, 2023). "The increased expression of TYR might serve as a salient marker of the low potential for metastasis in melanoma, owing to the downregulation of melanoma cell migration, cell survival, epithelial-mesenchymal transition, and tumorigenesis." (PMID 37217516, 2023). "In addition to its antioxidant activity and cytotoxicity, kaempferol’s tyrosinase inhibitory activity has been described against B16 melanoma cells." (PMID 37110512, 2023). ", as a regulatory component on melanin synthesis and tyrosinase activity of B16F10 melanoma cells." (PMID 37375695, 2023). "At the same time, an increase in tyrosinase activity was found in melanoma." (PMID 38067245, 2023).
melanoma (continued). "Furthermore, 39a was able to reduce cellular TYR activity in B16F10 melanoma cells as well as melanin synthesis." (PMID 37240442, 2023). "A clinical trial presented by Lembcke Perez Prieto in 2013 evaluated a human tyrosinase anti-melanoma vaccine, Oncept® (Merial Limited, Athens, GA, USA), in 10 horses bearing melanomas; the vaccine presented tumor burden reductions and was apparently safe and well tolerated in horses." (PMID 36670786, 2023). "The Oncept melanoma vaccine is xenogeneic DNA vaccine targeting tyrosinase." (PMID 36356074, 2022). "Finally, we evaluated the effects of ITMFAb on melanin production and tyrosinase activity in B16BL6 melanoma cells exposed to α-MSH (an inducer of melanin synthesis)." (PMID 36422527, 2022). "Tissue differentiation antigens are expressed by tumor cells and normal cells of the same tissue origin as tumor cells, such as prostate-specific antigen (PSA) expressed in the prostate gland and prostate cancer, melanoma antigens tyrosinase expressed by normal melanocytes, and melanoma cells." (PMID 35303904, 2022). "Additionally, both tyrosinase agonist 2-ETZ and tyrosinase substrate L-tyrosine significantly increased MITF, Tyrosinase, TYRP1 and TYRP2 expression and tyrosinase activity in parental B16 melanoma cells." (PMID 35265199, 2022). "Mainly, melanoma cells show increased levels of tyrosinase expression." (PMID 35204163, 2022). "B16F10 murine melanoma cells were used to investigate whether these two compounds display tyrosinase inhibitory activities and anti-melanogenesis effects in cells." (PMID 35242283, 2022). "Genetically engineered models of melanoma development and metastasis have also been reported, including tyrosinase-specific Braf p.V600E/Pten knockout mice, which is a model of developing malignant melanoma in which antioxidant administration promotes LN metastasis." (PMID 35915077, 2022). "Furthermore, quercetin, one of the active compounds of FBT, enhances melanogenesis by increasing tyrosinase activity in human melanoma cells and normal human melanocytes." (PMID 35326249, 2022). "In a study on xenograft models to stimulate awakening in dormant cells, thus making them more susceptible to treatment, methotrexate was reported to favor the phenotypic switch from a MITF low to an MITF high state, thus sensitizing melanoma cells to a tyrosinase-processed antifolate prodrug." (PMID 35565234, 2022). "The activity difference with our result on cell viability may result in the difference of origins of the tyrosinase (cultured human melanoma cells/B16F10 mouse malignant melanoma cells) and cultured time with α-arbutin (6 d/2 d)." (PMID 35326152, 2022). "In addition, the proanthocyanidins and condensed tannins in the seed coat of MB show a good inhibitory effect on the tyrosinase activity and melanogenesis of B16 mouse melanoma cells." (PMID 35369078, 2022). "Furthermore, A12 (100 μM) presented effective inhibitory effect on tyrosinase in B16 melanoma cells with inhibition of 33.48%, which was equivalent to that of Kojic acid (39.81%)." (PMID 35783205, 2022). "Moreover, treatment with Cpd1 promoted the expression of the melanocyte-specific tyrosinase gene specifically sensitizing melanoma cells for the tyrosinase-processed antifolate prodrug 3-O-(3,4,5-trimethoxybenzoyl)-(–)-epicatechin (TMECG)." (PMID 35650266, 2022). "However, those compounds also exhibited tyrosinase-independent cytotoxicity against an amelanotic SK-Mel-24 melanoma and an ovarian cell line." (PMID 36428680, 2022). "Thus, if tyrosinase activity is lost or decreased, melanoma would more easily grow and invade other tissues." (PMID 36556369, 2022). "Moreover, we found that GM can inhibit the expression of tyrosinase in a dose-dependent manner to achieve a more efficient synergistic treatment of melanoma." (PMID 35875081, 2022).
melanoma (continued). "The present study investigated the antimelanogenic effects of miglitol and the trehalase inhibitor validamycin A. Miglitol in isolation exhibited no cytotoxicity and significantly reduced the melanin production and intracellular tyrosinase activity in B16F10 melanoma cells." (PMID 36615308, 2022). "To test if the putative ligands expressed by cancer lines could suppress the T cell response, we used engineered human T cells transduced with a TCR (1383i) specific for the melanoma antigen tyrosinase." (PMID 35290663, 2022). "Thus, after exome sequencing of a set of melanoma patients and healthy control individuals, we identified rs1042602, an SNP within TYR, as a good candidate." (PMID 36556369, 2022). "Interestingly, catechin is known to inhibit melanin synthesis in B16F10 melanoma cells and tyrosinase expression." (PMID 35919819, 2022). "However, the inhibitory type of α-arbutin against human tyrosinase (human malignant melanoma cells, HMV-II) was indicated to be competitive in another study." (PMID 35326152, 2022). "Furthermore, the MITF and tyrosinase enzyme are responsible for pigmentation in both nevi and melanoma cells with a proliferative phenotype." (PMID 35956175, 2022). "Furthermore, A12 (100 μM) presented effective inhibitory on tyrosinase in B16 melanoma cells with an inhibition rate of 33.48%, which was equivalent to that of kojic acid (39.81%)." (PMID 35783205, 2022). "Notably, 27% of patients with stage III or stage IV melanoma who were immunized using dendritic cells loaded with mRNA encoding the melanoma-associated antigens MAGE-A3, MAGE-C2, tyrosinase, gp100, and TriMix showed tumor regressions." (PMID 35289317, 2022). "Moreover, during progression of advanced melanotic melanomas, levels of tyrosinase or different intermediates of melanogenesis are increased in the serum, contributing to general melanosis." (PMID 35359389, 2022). "Our results also suggested that DDX3 might promote melanogenesis in H2O2-treated SK-Mel-2 human melanoma cells by binding to tyrosinase." (PMID 36296601, 2022). "In addition, western blot analysis showed that at 60 μg/mL dose of PP60 significantly reduced L-DOPA-induced tyrosinase expression in melanoma cells." (PMID 36091602, 2022). "Malignant melanoma possesses a unique metabolic pathway, the synthesis of melanin pigments, which are formed by the conversion of tyrosine to dopaquinone in the presence of tyrosinase (EC 1.14.18.1)." (PMID 36428680, 2022). "Finally, the cytotoxicity of two tyrosinase inhibitors and two tyrosinase activators was assessed in melanoma cell lines (B16F1/B16F10), as well as their ability to moderate tyrosinase activity and affect melanin production." (PMID 36009312, 2022). "In humans, tyrosinase overexpression leads to the accumulation of melanin in skin and can trigger hyperpigmentation manifesting as freckles, melasma, age spots, postinflammatory hyperpigmentation, or melanoma." (PMID 35624809, 2022). "Furthermore, approaches based on targeting tyrosinase activity to inhibiting multi-organ metastasis of melanoma cells need to be designed and validated." (PMID 35265199, 2022). "The 2-fluorophenylacetamide containing furan-oxadiazole compound 5a may be considered as a potential lead for tyrosinase inhibition with lesser side effects as a skin whitening and malignant melanoma anticancer agent." (PMID 36142889, 2022).
melanoma (continued). "In addition, we evaluated the effect of EU fractions on tyrosinase activity and melanogenesis in α-melanocyte-stimulating hormone-induced B16-F10 melanoma cells." (PMID 33804361, 2021). "Therefore, thanks to this cross-validation among different databases, MAOA, PARP1 and TYR represent the best CMT with significant differential expression in melanoma vs. control biopsies." (PMID 34199192, 2021). "Taking this in mind, Choi and collaborators demonstrated that compounds containing the β-phenyl-α,β-unsaturated carbonyl scaffold exhibited potential antimelanoma properties, acting through the inhibition of tyrosinase activity and suppression of melanin production in B16-F10 melanoma cells." (PMID 34831311, 2021). "Tyrosinase is a melanin-producing enzyme found in melanocytes and melanoma cells." (PMID 35003391, 2021). "TPC2 inhibition thus provides a twofold benefit in melanoma prevention and treatment by increasing, through interference with tyrosinase activity, the synthesis of UV blocking melanin in melanosomes and by decreasing MITF-driven melanoma progression by increased GSK3β-mediated MITF degradation." (PMID 33875769, 2021). "Excessive accumulation of melanin pigments or the overexpression of tyrosinase may result in skin-related disorders such as aging spots, wrinkles, melasma, freckles, lentigo, ephelides, nevus, browning and melanoma." (PMID 34946631, 2021). "Incubation of 50 μm rosmarinic acid with B16 melanoma cells for 48 h resulted in a significant increase in melanin content and tyrosinase protein expression, the mechanism being that rosmarinic acid induces melanin synthesis by activating the PKA/CREB signaling pathway via phosphorylation." (PMID 34858164, 2021). "Accordingly, the present study suggests that PA may effectively downregulate tyrosinase activity in α-MSH-induced melanoma cells, resulting in a decrease in cellular melanin synthesis." (PMID 33917915, 2021). "Since our study showed a link between HuR and MITF and that HuR is known to regulate HIF-1α and HIF-1α-regulated target genes such as VEGF, it will be of interest to investigate the role of HuR in melanogenesis and melanogenesis regulated tyrosinase in melanoma." (PMID 33418925, 2021). "Finally, to complete the research bearing in mind a comprehensive approach to anti-melanoma therapy, the anti-inflammatory and anti-tyrosinase properties of usnic acid enantiomers were also examined." (PMID 34577645, 2021). "Using a variety of pH-sensitive fluorescent probes, we found that downregulation of MGRN1 expression significantly increased the pH of acidic organelles, thus accounting for the high specific activity of TYR in the melanosomes of MGRN1-deficient melanocytes and melanoma cells." (PMID 34921635, 2021). "Participants with resected stage IIB-IV melanoma were vaccinated with seven long melanoma peptides (LPV7) from tyrosinase, gp100, MAGE-A1, MAGE-A10, and NY-ESO-1, each containing a known MEP for CD8+ T cells, plus a tetanus helper peptide (Tet) restricted by Class II MHC." (PMID 34413169, 2021). "Therefore, to detect the in vitro effect of PA on melanin synthesis, B16F10 melanoma cells were treated with 4 mM PA for 48 h, with the decreased expression of the tyrosinase in PA treated melanoma cells compared to the control." (PMID 34099789, 2021). "Thus, isolated cells display specific phenotypical and functional features of melanocytes/melanoma cells such as tyrosinase and Melan-A expression and melanin production." (PMID 34944864, 2021). "This case highlights the fact that, although tyrosinase is reported to be less sensitive than S100 protein, it is one of the most specific immunostains that may prove useful when the diagnosis of malignant melanoma is in doubt." (PMID 34449584, 2021). "Additionally, quercetin can be metabolized by tyrosinase, which is expressed in melanocytes, into additional anti-cancer compounds, potentially increasing its potency specifically for melanoma." (PMID 34066966, 2021).
melanoma (continued). "In our earlier study, we reported on the capacity of four novel CMC analogs to inhibit tyrosinase enzyme activity in an acellular system as well as melanogenesis in B16F10 mouse melanoma cells; we have further begun to elucidate the mechanisms by which they inhibit melanogenesis." (PMID 34205035, 2021). "The overexpression of TYR and TRP 1 is significantly associated with the risk of melanoma." (PMID 34436092, 2021). "In a study in human melanomas, only 74% of metastatic melanomas expressed TYR RNA." (PMID 34422947, 2021). "Expression of tyrosinase, tyrosinase-related protein 1 (TRP-1) and tyrosinase-related protein 2 (TRP-2), and microphthalmia-associated transcription factor was inhibited in B16F10 melanoma cell lines." (PMID 33923988, 2021). "As can be seen, these cells expressed TYR mRNA at a level similar to the MeWo melanoma cell line." (PMID 34944864, 2021). "In silico screening of genes potentially involved in the effects of Caff, validated by in vitro analysis with two MICs models exposed to caffeine to evaluate their behaviors, confirms a key role of TYR and melanin, possibly acting through an immunomodulatory action, on melanoma growth and evolution." (PMID 34199192, 2021). "This was followed by the identification of tyrosinase mRNA in the serum of melanoma patients." (PMID 33593440, 2021). "•Soluble tyrosinase degradation is EDEM2 dependent in melanoma cells." (PMID 34332121, 2021). "In addition, p-coumaric acid, an active compound of Sasa quelpaertensis Nakai, has been proved that this compound strongly inhibited tyrosinase activity and reduced melanin production in melanoma cells." (PMID 34563052, 2021). "Similarly, miR-330-5p downregulated TYR in melanoma cells and normal melanocytes, inducing depigmentation without affecting cell proliferation." (PMID 34198907, 2021). "Anti-tyrosinase has been studied in antibodies in melanoma and vitiligo." (PMID 34885832, 2021). "Interestingly, regional lymph node metastases showed positive S100 protein, MITF, and tyrosinase staining, further emphasizing the protean nature of melanoma." (PMID 34449584, 2021). "The expression of TYR RNA has been detected in human melanoma cell lines." (PMID 34422947, 2021). "Tyrosinase attracted the interest of immunologists because it was known that melanoma patients could form an immune response to antigens related to melanogenesis." (PMID 34885832, 2021). "In addition, both the previous and current results confirm that PA not only inhibits cell-free tyrosinase activity but also inhibits intracellular tyrosinase in α-MSH-induced melanoma cells." (PMID 33917915, 2021). "Moreover, a set of triazene prodrugs has also shown antiproliferative properties towards MNT-1 and SKMEL-30 human melanoma cell lines expressing tyrosinase." (PMID 34831311, 2021). "Melanoma-associated mRNA markers (MAGE-3, MART-1, and tyrosinase) could be detected by RT-PCR in approximately 50% of patients with melanoma who developed IMD during the follow-up period." (PMID 34885083, 2021). "Since melatonin is a tyrosinase activity inducer, it could be of clinical interest to determine whether the indoleamine modulates the sensitivity of human melanoma cells to conventional chemotherapy." (PMID 32674468, 2020). "TYR has become commonplace in the diagnosis of melanoma for its high sensitivity and specificity." (PMID 32429485, 2020). "The discovery of novel tyrosinase inhibitors with an ability to regulate melanogenesis is of special interest, as the excessive production of melanin leads to hyperpigmentation of the skin in the form of freckles, the so-called “age spots” and melanoma." (PMID 32486036, 2020). "Therefore, to evaluate this clustering effect, calixarbutin was compared with arbutin in two anti-tyrosinase and anti-melanoma tests." (PMID 33224228, 2020).